CD4 (CD4 molecule)
Diseases named in the same sentence as CD4 in open-access papers (continued):
Sharing a sentence is not in itself a finding about the gene and the disease.
Chagas disease (continued). "Therefore, regulatory CD4+CD25+ T cells play a positive role in the development of acute T. cruzi infection by inducing immunosuppressive activity that controls early cardiac inflammation during acute Chagas disease, prolonging survival, but at the same time promoting parasite growth." (PMID 23509755, 2013). "CD4+ and CD8+ T responses are involved in the control of the acute Trypanosoma cruzi infection and keep the parasite burden under control during the chronic phase of the infection." (PMID 22574131, 2012). "T-cell responses, mediated by both CD4+ and CD8+ T cells, in Chagas disease are rather complex." (PMID 37987164, 2024). "However, little is known about the role of these molecules in activating adaptive immunity mediated by CD4+ and CD8+ T lymphocytes and their subsets during the chronic phase of Chagas disease." (PMID 35665256, 2022). "Although the expression of CD69 on naïve CD4+ T cells has been published in some pathological conditions, such as Graves’ disease and autoimmune thyroiditis, no reports were found in Chagas disease." (PMID 36447264, 2022). "Thus, using monoclonal blocking antibody for CD80 and CD86 receptors, we assessed the functional phenotypic profile of CD4+ T and CD8+ T lymphocytes and their subsets from cultures of PBMC after TRYPO stimulation from healthy and Chagas disease patients." (PMID 35665256, 2022). "CD4+CD8high T cells have been described to be a more activated population of CD4+CD8+ T cells when HLA-DR and CD38 activated markers are measured in the context of Chagas disease." (PMID 29750791, 2018). "Among patients with positive serology for Chagas disease, patients with reactivation of Chagas disease had low levels of CD4+ T-cells counts compared to patients without reactivation, as previously observed." (PMID 26919324, 2016). "Moreover, severe/moderate cardiomyopathy patients showed lower frequency of CD4+CD25− T cells expressing CTLA-4 (P = 0.035) than free/mild cardiomyopathy patients, and Bz treated Chagas' disease patients." (PMID 22545173, 2012). "Lastly, although the function of peripheral CD4+CD8+ T-cell population remains to be defined in vivo, their presence may contribute to the immunopathological events found in both murine and human Chagas disease." (PMID 22505943, 2012). "Upon binding to HLA class I molecules, CD4+ T cells expressing LIR-1 might be inhibited, thus affecting macrophage activation and CD8+ T cell responses which are crucial to control Trypanosoma cruzi infection." (PMID 22574131, 2012). "Recent studies suggest that indeterminate Chagas' disease patients have higher frequency of CD4+CD25high T cells in comparison to cardiac and non-infected individuals in their peripheral blood." (PMID 22545173, 2012). "Considering that most intra-TNC thymocytes are immature CD4+CD8+ cells, one could raise the hypothesis that the migratory capacity of these cells is enhanced in murine Chagas disease." (PMID 16846255, 2006). "Thus, the expansion of CD69+CD4+ T cells during Chagas disease is probably not due to recirculation of TRM." (PMID 36447264, 2022). "A nonredundant function for CD4+ T cells is less well established in murine models of Chagas disease (47, –, 49), although in humans with untreated HIV coinfections, parasites become easily detectable in the bloodstream and can result in central nervous system (CNS) pathology." (PMID 34780279, 2022). "ATP induces cell death in CD4+/CD8+ double-positive thymocytes during the acute phase of Trypanosoma cruzi infection in Chaga's disease and may play a role in the thymus atrophy that occurs in Chaga's disease." (PMID 24312014, 2013). "In patients with Chagas disease, regardless of the clinical form, the same proportion of CD28 on Th1, Th2, Th17, and CD4+ Treg was observed in the three cultures of PBMC evaluated." (PMID 35665256, 2022).
Chagas disease (continued). "Likewise, the expression of P-selectin counter-receptor PSGL-1 was not altered on CD4+ and CD8+ T cells of Chagas disease patients when compared with that of uninfected healthy subjects." (PMID 31199841, 2019). "However, after T. cruzi stimulation, a decrease in CD95L expression in CD4+ CD95+ T cells only in IND patients was seen and higher levels of CD95L receptor in patients with Chagas disease were also observed, regardless of the clinical form." (PMID 30405039, 2018).
Chronic colitis (66 papers, 2009 to 2025). A chronic inflammatory disease of the large intestine (colon, cecum and rectum). "We have demonstrated that the accumulation of Treg in the mucosal inductive sites (i.e., MLN) is associated with prevention of chronic colitis caused by the adoptive transfer of CD4+CD45RBhi T cells in SCID mice." (PMID 20537136, 2010). "IL-22-producing CD4 T cells are found to be pathogenic in a model of chronic colitis." (PMID 28408906, 2017). "Additionally, we performed a complementary experiment and explored whether deficiency of Gpr65 in CD4+ T cells affected the development of chronic colitis in mice." (PMID 35343079, 2022). "To this end, we established a chronic colitis model in Rag1−/− mice reconstituted with syngenetic CD45RBhigh CD4+ T cells and administered IPA or water orally every other day via gavage." (PMID 39956891, 2025). "During chronic colitis, CD4+ and CD8+ T cells showed an abnormal mitochondrial phenotype which was restored during remission." (PMID 41007657, 2025). "We further determined the role of Treg-derived AREG in intestinal fibrosis using the CD45RBhi CD4+ T cell adoptive transfer model to induce chronic colitis in Rag−/− mice." (PMID 40247299, 2025). "The depletion of B cells reduced intestinal inflammation by inhibiting pro-inflammatory cytokine production in CD4+ T cells in a chronic colitis mouse model." (PMID 40331987, 2025). "To determine if T cell intrinsic TLR7 signaling contributes to the development of chronic colitis, we transferred CD4+ CD45RBhi naive T cells isolated from wild-type (WT) or Tlr7-/- mice into Rag1-/- mice and monitored for development of inflammatory disease." (PMID 39464882, 2024). "The colonic samples obtained from mice with acute colitis were characterized by higher macrophage infiltration and MPO activity, whereas infiltration of CD4 + lymphocytes was substantially lower than in reactivated, chronic colitis." (PMID 37086302, 2024). "Whereas transfer of purified CD4 + lymphocytes from IL-10−/− mice to immunodeficient RAG mice results in the development of chronic colitis, with the CD4 + population as the predominant culprit." (PMID 36869359, 2023). "In murine models it was shown that long-lived colitogenic CD4+ Tm cells residing outside the intestine participate in the perpetuation of chronic colitis." (PMID 37456566, 2023). "Consistently, several studies confirmed the increase of MDSCs in the peripheral blood, bone marrow and spleens by establishing chronic colitis in C.B-17 SCID mice after adoptive transfer of CD4+CD45RBhigh T cells, or in BALB/c mice after DSS administration." (PMID 36189262, 2022). "IL-7 activates IL-7 receptor α and induces proliferation and long-term survival of effector memory CD4+ T cells, leading to chronic colitis." (PMID 33597887, 2020). "Chronic colitis, with CD4+ cell mucosal infiltration, was found in 85% of PD patients with constipation." (PMID 32575365, 2020). "To determine the effects of blocking the function of IL-17A in chronic colitis, we induced colonic inflammation in Rag2−/− mice via a transfer of CD4+CD45RBhi T cells isolated from WT or Il17a−/− mice." (PMID 31941937, 2020). "The potential benefit of MT-1303 for IBD was assessed using immunodeficient SCID mice with chronic colitis induced by adoptive transfer of CD4+CD45RBhigh T cells from BALB/c mice." (PMID 31805144, 2019). "In this report, we showed that BBR ameliorated CD4+ T cell-related chronic colitis in a mouse model and revealed the relationship between BBR and AMPK, including its metabolic pathway, through in vitro and in vivo experiments." (PMID 31417110, 2019). "In the present study, we evaluated the effects of MT-1303 on chronic colitis in immunodeficient SCID mice induced by adoptive transfer of CD4+CD45RBhigh T cells from BALB/c mice, an animal model of IBD." (PMID 31805144, 2019).
Chronic colitis (continued). "Oral administration of MT-1303 at 0.1 and 0.3 mg/kg was efficacious against chronic colitis induced by adoptive transfer of CD4+CD45RBhigh T cells, a murine IBD model, and its efficacy was comparable to that of an anti-mTNF-α mAb." (PMID 31805144, 2019). "In summary, we showed for the first time that BBR ameliorated CD4+ T cell-related chronic colitis in a mouse model with changes in gut microbiota via AMPK activity, possibly induced by the inhibition of OXPHOS, according to in vitro and in vivo experiments." (PMID 31417110, 2019). "Overall, this study demonstrated that MT-1303 has comparable efficacy to an anti-mTNF-α mAb against chronic colitis induced by adoptive transfer of CD4+CD45RBhigh T cells." (PMID 31805144, 2019). "Alternatively, in a chronic colitis model that is induced by the adoptive transfer of memory CD4+ T cells, a proinflammatory role of memory T cell-derived IL-22 was proposed." (PMID 29075900, 2018). "Despite validation of a protective role of IL-22-producing CD4 T cells in acute colitis, paradoxically it can also contribute to intestinal pathology during chronic colitis." (PMID 28408906, 2017). "In our study, HQT treatment was associated with a significant increase in the number of CD4+CD25+ Foxp3+ Treg cells and in the expression level of Foxp3 in the colon of mice with DSS-induced chronic colitis." (PMID 27982094, 2016). "The importance of Teffector cells in chronic colitis was also implied from data showing that infusion of anti-CD4 mAb into CD200KO and CD200RKO mice improved weight gain in these mice." (PMID 26841120, 2016). "Cytokine production from MACS- column enriched CD4+ cells isolated from LP cells in this chronic colitis model contrasted with data from mice with acute colitis." (PMID 26841120, 2016). "For example, others have used an adoptive IL-10−/− CD4+ T cell transfer model of chronic colitis in which piroxicam is administered to induce acute colitis." (PMID 25247786, 2014). "In summary, our results indicate that the CD69 expressed on CD4 T cells plays a critical role in the development of DSS-induced acute and chronic colitis via the efficient migration of activated CD4 T cells into the colon." (PMID 23785429, 2013). "In particular, we have been able to demonstrate that TL1A synergizes with IL-23 to induce IL-17 production by CD4+ T cells in a mouse model of chronic colitis." (PMID 19262684, 2009). "Chronic colitis was induced by dextran-sulphate-sodium (DSS) or transfer of CD4+CD62L+ cells into RAG1−/−-mice." (PMID 19787068, 2009). "To investigate this, we utilized a chronic colitis CD4+ T cell transfer model in Rag1−/− mice." (PMID 40887825, 2025). "Moreover, oral administration of IPA also resulted in a marked decrease in HSP70 protein expression in LP CD4+ T cells from a chronic colitis mouse model induced by the adoptive transfer of CD45RBhighCD4+ T cells." (PMID 39956891, 2025). "CD4+TRM was significantly increased in chronic colitis and decreased in EZH2fl/flCD4cre mice." (PMID 38243324, 2024). "Therefore, to further analyze the improvement effects of (R)-sal in inflammation, we measured the expression of immune cell CD4 leukocytes in chronic colitis colon tissue by immunofluorescence." (PMID 35178163, 2022). "Although w and others have shown that adoptive transfer of naïve syngeneic CD4+ T cells into untreated RAG1-/- recipients are capable of inducing chronic colitis, the onset and severity of disease is critically dependent upon the composition of intestinal bacteria." (PMID 34358240, 2021). "Interestingly, UAMC-00050 showed anti-inflammatory effects in a murine CD4+CD25−CD62L+ T-cell transfer model for chronic colitis and a rat model of dry eye syndrome." (PMID 34072320, 2021).
Chronic colitis (continued). "Note that in this chronic colitis model, transfer of Treg-depleted CD4+CD45RBlo T cells into RAG-1-/- mice was characterized by a Th1<Th17 cytokine signature in the colon tissues, whereas transfer of CD4+CD45RBhi naïve T cells demonstrated a Th1>Th17 cytokine signature." (PMID 34992594, 2021). "Se suppressed inflammation in chronic colitis mice by upregulating CD4+CD25+ Treg cells." (PMID 34444651, 2021). "In this study, we showed that the inhibitory efficacy of MT-1303 on chronic colitis induced by adoptive transfer of CD4+CD45RBhigh T cells was comparable to that of an anti-mTNF-α mAb, indicating that MT-1303 may have therapeutic potential for IBD." (PMID 31805144, 2019). "IL-7 exacerbates chronic colitis in mice by inducing expansion of mucosal CD4+ IL-7Rhigh T cells." (PMID 28770173, 2017). "Indeed in chronic colitis, relatively equivalent cytokine levels were observed in CD4+ and CD11c+, CD11b+ cells." (PMID 26841120, 2016). "We first noticed that H2M−/− CD4 T cell recipients rapidly lost body weight, even starting 7 days post transfer, which is in good contrast with WT T cell recipients that typically develop chronic colitis 4–6 weeks after the transfer." (PMID 25313460, 2014). "Interestingly, TiO2 NPs decreased the CD4+ T cells, T regs, and macrophages in the mesenteric lymph nodes and increased neutrophil gelatinase-associated lipocalin (LCN2) levels in mice aggravating the DSS-induced chronic colitis." (PMID 33669592, 2021). "Besides, IL-17A blockage may increase the proportion of RORγt+ ILCs (which include CD4+LTi cells) and ILC1s, thereby eventually worsening chronic colitis." (PMID 31941937, 2020). "However, IL-7 exacerbates chronic colitis, with expansion of mucosal CD4+IL-7Rhigh T cells in mice." (PMID 27424033, 2016). "Thus, CD69+ CD4 T cells may be involved in the disease progression of chronic colitis or the recovery from acute colitis." (PMID 23785429, 2013). "Together, our findings here reveal an atypical mitochondrial phenotype of colonic CD4+ and CD8+ T cells during chronic colitis that is restored during remission." (PMID 41007657, 2025). "Together, our data provide evidence of an atypical mitochondrial phenotype of colonic CD4+ and CD8+ T cells during chronic colitis that returns to the initial state during the remission phase of the disease." (PMID 41007657, 2025). "After 9 weeks of DSS-induced chronic colitis, a decreased percentage of TRM in CD4+IELs, CD4+LPLs and CD8+LPLs were observed among T cells originating from Ezh2fl/fl ERT2-Cre mice compared with that of cells of WT origin." (PMID 38243324, 2024). "Remarkably, it was found a decline in both activated (CD44 +) T CD4 and T CD8 cells in the MLN of mice with chronic colitis compared to controls, suggesting their mobilization to the lamina propria." (PMID 35705557, 2022). "T cells play a crucial role in IBD progression since levels of activated CD4+ T cells are higher in both IBD and experimental models of chronic colitis." (PMID 35631522, 2022). "The percentages and absolute numbers of CD25-expressing T cells (CD4+CD25+) and CD25-expressing B cells (B220+CD25+) in T-LPLs were drastically higher in the MLN of the IL-33-treated chronic colitis group than that of the control group." (PMID 30539029, 2018). "In a chronic colitis model, TNF-α stimulated the IL-22BP expression in CD4+ T cells, leading to the suppression of IL-22-dependent mucosal healing." (PMID 29075900, 2018). "To analyze the subsets of splenic and PB T cells that suffer apoptosis following MORE and MOHRE treatment in chronic colitis mice, we applied annexin V+/PI+ among total T cell (CD3+), helper T cells (CD3+CD4+) and cytotoxic T cell (CD3+CD8+) in spleen and PB." (PMID 28824631, 2017). "In mice, neutrophils isolated from chronic colitis lesions have been shown to express MHC II and CD86 and exhibit an APC capacity to present peptide antigen to CD4 T cells." (PMID 24278484, 2013).
Chronic colitis (continued). "In this context, it is not surprising that BM can serve as a reservoir of the inflammatory T cells, as was found by the transfer of chronic colitis to severe combined immunodeficiency (SCID) mice by BM memory CD4+ cells, but also as a source of CD4+CD25+ Tregs." (PMID 32111105, 2020). "In accordance with above observation, our data demonstrated that the expression level of IL-10, the absolute number and percentage of CD4+CD25+ and CD4+IL-10+ Tregs in MLN of mice with DSS-induced chronic colitis, were strikingly higher in the IL-33 group than in PBS group." (PMID 30539029, 2018). "Furthermore, we detected IFN-γ or IL-17A-producing CD4+ T cells in the MLN of IL-33-treated and untreated chronic colitis mice." (PMID 30539029, 2018). "We also assessed mitochondrial activity in LP-CD4+ T cells isolated from chronic colitis mouse model induced by the adoptive transfer of CD45RBhighCD4+ T cells following oral IPA treatment, showing a significant reduction in mitochondrial activity in IPA-treated CD4+ T cells." (PMID 39956891, 2025). "The results are consistent with the investigation of H. polygyrus infection-induced Tregs, in which adoptive transfer of Tregs from the cLP of H. polygyrus-infected mice as opposed to uninfected-mice significantly inhibited chronic colitis induced by CD4+CD25– T cells in Rag1 KO mice." (PMID 34336843, 2021). "In the intestinal lamina propria, CD4+LTi cells may play a major role in the development of chronic colitis in the absence of IL-17A." (PMID 31941937, 2020). "In chronic colitis, 6-TG induced apoptosis of Th (CD3+CD4+CD8-) cells while AZA did not." (PMID 21545711, 2011). "However, the amino acid transporter activity of CD4+ and CD8+ T cells and eosinophils and neutrophils, analyzed by using Boronophenylalanine (BPA) staining and flow cytometry, was not significantly altered during acute and chronic colitis." (PMID 41007657, 2025).